KDR (kinase insert domain receptor)
Diseases named in the same sentence as KDR in open-access papers (continued):
Sharing a sentence is not in itself a finding about the gene and the disease.
diabetic retinopathy (23 papers, 2012 to 2025). "This aligns with previous research that highlighted the role of KDR polymorphisms in various micro- and macrovascular complications, including diabetic retinopathy, cardiovascular disease, and CVD." (PMID 39273385, 2024).
pulmonary hypertension (23 papers, 2006 to 2025). Increased pressure within the pulmonary circulation due to lung or heart disorder. "According to the pulmonary hypertension gene curation expert panel of pulmonary hypertension of ClinGen, the association of BMPR2, KCNK3, KDR, SMAD9, and TBX4 and PH is definitive, GDF2 is strong, and AQP1 has a limited disease relationship." (PMID 35627312, 2022).
soft tissue sarcoma (23 papers, 2010 to 2025). A malignant neoplasm arising from muscle tissue, adipose tissue, blood vessels, fibrous tissue, or other supportive tissues excluding the bones. "A recent example is anlotinib, which inhibits VEGFR1, VEGFR2/KDR, VEGFR3, c-kitPDGFR1 and FGFR, which is an example of Chinese developed drugs, being registered for treatment of NSCLC and soft tissue sarcoma." (PMID 30544701, 2018).
neuroblastoma (20 papers, 2006 to 2025). Neuroblastoma (NB) is the most common solid, extracranial childhood tumor. "Overall, the roles of KDR-mediated signaling in neuroblastoma cell homeostasis await future elucidation." (PMID 34716856, 2022). "Finally, KDR (or VEGFR2) is an established proto-oncogene in several solid tumor models, including neuroblastoma, due to its central role orchestrating tumor neo-angiogenesis." (PMID 34716856, 2022). "VEGF signaling plays a regulatory role in neuroblastoma angiogenesis via a paracrine mechanism through two specific tyrosine kinase VEGF receptors: VEGFR-1 (or Flt-1) and VEGFR-2 (or KDR) at the surface of the endothelial cells." (PMID 21876694, 2012).
meningioma (19 papers, 2013 to 2025). A generally slow growing tumor attached to the dura mater. "KDR mRNA and protein expression levels have been investigated several times in meningiomas and found contradicting results." (PMID 31470906, 2019). "Taken together, APC, KDR and GSE1 mutations might contribute to meningioma growth, however, validation by Sanger sequencing and functional analyses are needed to strengthen these preliminary findings." (PMID 31470906, 2019). "The T cells in meningioma showed five additional drug-target kinases that were significantly increased in expression compared to VS (CSF1R, LYN, ABL, MAP2K1, and BRAF), whereas VS had only one drug-target kinase, KDR." (PMID 41437121, 2025).
medullary thyroid cancer (18 papers, 2009 to 2025). "Vandetanib and cabozantinib, both multi-kinase inhibitors with RET activity, are approved for use in medullary thyroid carcinoma, but additional pharmacological activities, most notably inhibition of vascular endothelial growth factor - VEGFR2 (KDR), lead to dose-limiting toxicity." (PMID 27429741, 2016).
rheumatoid arthritis (17 papers, 2009 to 2025). A chronic, systemic autoimmune disorder characterized by inflammation in the synovial membranes and articular surfaces. "We investigated kinase insert domain-containing receptor (KDR) polymorphisms and protein levels in relation to susceptibility to and severity of Rheumatoid Arthritis (RA)." (PMID 31405022, 2019). "We investigated, for the first time to our knowledge, the potential involvement of the KDR (VEGFR2) gene polymorphisms in rheumatoid arthritis susceptibility and severity." (PMID 31405022, 2019). "In summary, our results suggested that examined KDR genetic variants may be associated with rheumatoid arthritis either by increased or decreased KDR protein expression levels." (PMID 31405022, 2019). "Finally, we identified 146 likely causal genes for rheumatoid arthritis, including CD4, FGFR1, and KDR, which have been reported as high risk factors by recent studies." (PMID 20727150, 2010).
squamous cell carcinoma (17 papers, 2008 to 2025). A carcinoma arising from squamous epithelial cells. "A few studies have described this substitution in KDR as an indicator of bad prognosis and lower overall survival, while the paper by Tinhofer in 2016 supports the hypothesis that it is a good prognostic factor in squamous cell carcinoma of the head and neck." (PMID 37046732, 2023).
endometrial cancer (16 papers, 2003 to 2023). Primary or metastatic malignant neoplasm involving the endometrium (mucous membrane that lines the endometrial cavity). "Taken together, MET mutations highly influence the clinical outcome of advanced endometrial cancer, and KDR and KRAS mutations exhibit additional impacts on patients with a MET mutation." (PMID 34439385, 2021). "Endothelial progenitor cell numbers (CD34, VEGFR2/KDR) in the peripheral blood of women with early endometrial carcinoma were significantly augmented compared with those of healthy control women, while circulating endothelial cell numbers (CD31, CD45) were similar in both groups." (PMID 30087246, 2018). "Vascular endothelial growth factor-1 binds VEGFR-1 (flt-1) but not VEGFR-2 (KDR), both of which are present in peritumoral endothelial cells of endometrial cancers." (PMID 12942123, 2003).
infantile hemangioma (16 papers, 2013 to 2024). "According to previous reports, KDR is an essential factor in the pathogenesis of infantile hemangiomas." (PMID 36422523, 2022).
papillary thyroid carcinoma (16 papers, 2015 to 2025). "They showed that coexpression of VEGF and two high-affinity tyrosine kinase receptors in VEGF signaling, namely, VEGFR-1/Flt-1 and VEGFR-2/KDR, were expressed in papillary thyroid carcinomas (PTCs), including follicular variants." (PMID 35923625, 2022).
lymphoma (15 papers, 2010 to 2025). A malignant (clonal) proliferation of B- lymphocytes or T- lymphocytes which involves the lymph nodes, bone marrow and/or extranodal sites. "It should be highlighted that MET, KDR (VEGFR) STK11 and BRAF are all upstream signaling components in the MAPK pathway and aberrant MAPK signaling is a known oncogenic mechanism in lymphoma." (PMID 29854308, 2018).
asthma (14 papers, 2010 to 2025). "KDR is involved in three of the secondary KEGG asthma pathways including PI3K-Akt signaling pathway, Calcium signaling pathway and MAPK signaling pathway; with the Ras signaling pathway additionally involved in these (KEGG)." (PMID 32185106, 2020). "Intriguingly, asthma only increased KDR protein compared to AR core targets, and these results strongly suggest that aloin may share similar molecular mechanisms for treating allergic rhinitis and asthma." (PMID 37781715, 2023). "The highly expressed stromal marker genes like KDR and LAMB1 in mesenchymal cells also indicated the presence of stromal cells in the mesenchyme following an asthma attack." (PMID 36439114, 2022). "The five identified target proteins, ESR1, KDR, LTA4H, PDE4D and PPARG, show evidence of involvement in the pathological expression of asthma, with three classified as receptors (ESR1, KDR, PPARG), and two categorized as enzymes (LTA4H, PDE4D) (KEGG, UniProt)." (PMID 32185106, 2020). "Each of the five identified target proteins, ESR1, KDR, LTA4H, PDE4D and PPARG, have established potential to play significant roles involving both the primary and secondary asthma pathways through many signaling cascade pathways." (PMID 32185106, 2020). "Computational molecular docking of DCT compounds identified five proteins (ESR1, KDR, LTA4H, PDE4D and PPARG) mutually targeted by asthma genes and DCT compounds and 155 docking connections associated with cellular pathways involved in the biological mechanisms of asthma." (PMID 32185106, 2020). "We compared the differential genes of 4 subtypes of cells after the asthma attack and found highly variable genes in MC1 were concentrated in biological processes, including cell migration and proliferation, which were also widely expressed in epithelial cells (e.g., KDR and LAMB1)." (PMID 36439114, 2022).
chordoma (13 papers, 2016 to 2025). Chordomas are rare malignant tumors arising from embryonic remnants of the notochord in axial skeleton. "Taken together, our results suggest that of the chordoma-implicated genes we successfully tested in our assay, only overexpression or misexpression of the chordoma-implicated EGFR and KDR RTKs is sufficient to trigger the onset of notochord hyperplasia." (PMID 31221659, 2019). "The Hub genes PDGFRB, KDR, and FGF2 are involved in the pathogenesis of chordoma via the Pi3k-Akt signaling pathway and the Rap1 signaling pathway." (PMID 32011476, 2020). "Hub genes PDGFRB, KDR, FGF2 and pi3k-akt signaling pathway, Rap1 signaling pathway will become a new target for the future treatment of chordoma." (PMID 32011476, 2020). "ULK4, NPR1 and CDKL4 were the top most expressed kinases in the Chor-IN-1 cell line, while FGFR3, KDR and WNK2 were less expressed or absent in Chor-IN-1 cells as compared to the other chordoma lines." (PMID 28835717, 2017).
gastric adenocarcinoma (13 papers, 2013 to 2025). "The receptor tyrosine kinases (RTKs) MET and vascular endothelial growth factor receptor 2 (VEGFR2/KDR) are emerging therapeutic targets in gastric adenocarcinoma." (PMID 23516391, 2013).
mesothelioma (13 papers, 2010 to 2025). A usually malignant and aggressive neoplasm of the mesothelium which is often associated with exposure to asbestos. "It has been shown that the expression of VEGFR-1/Flt-1, VEGFR-2/KDR, Nrp-1 and Nrp-2 remains unchanged during the malignant transformation of MCs (e.g. mesothelioma)." (PMID 23585849, 2013).
depression (12 papers, 2011 to 2024). "To examine the association between the VEGF pathway and depression, we genotyped polymorphisms and measured the plasma concentrations of VEGF, KDR, and FLT1 proteins." (PMID 36559251, 2022). "Levels of circulating CD34+CD133+KDR+ EPCs and endothelial colony-forming units in patients with depression were lower than that of healthy subjects." (PMID 34421539, 2021). "Afterwards, we assessed whether genetic polymorphisms of VEGF and its receptors, KDR and FLT1, are associated with depression and severity of symptoms, considering the presence of early life stress in these associations (ELS)." (PMID 36559251, 2022). "In the present study, we aimed to assess whether plasma levels of VEGF, KDR, and FLT1 were associated with depression risk, symptoms intensity, and suicide attempts." (PMID 36559251, 2022).
Lewis lung carcinoma (11 papers, 2010 to 2025). "They observed that DHA induced apoptosis in Lewis lung carcinoma (LLC) cells and affected the expression of VEGF receptor KDR/flk-1." (PMID 33613116, 2021).
astrocytoma (10 papers, 2009 to 2023). "Variants of KDR rs2071559‐C and rs2305948‐T may increase the risk of astrocytomas, whereas mutants of KDR rs1870377‐A may reduce the risk of astrocytomas." (PMID 37803932, 2023). "Also, the KDR rs2071559 G allele correlates with an increased risk of astrocytomas, while individuals with the A allele and genotype TA +AA of rs1870377 showed a protective effect against astrocytomas." (PMID 37803932, 2023). "Except for CCND2, FLT1, FOXC2, KDR, KRT14, and TEK, the mRNA expression ratio of cancer pathway-associated genes in the astrocytoma grade III cell line (SW1088) was comparable to that of other tumour cell lines." (PMID 36142793, 2022). "CDKN2A/B deletion was also observed in Res259 astrocytoma cells, which also contained the well-described 4q12 amplicon, resulting in high level gains of the oncogenes PDGFRA and KIT, and low-level gain of a region including KDR/VEGFR2." (PMID 19365568, 2009).
chronic myeloid leukemia (10 papers, 2015 to 2025). "Additionally, following an ELISA analysis, ART’s inhibitory effects on vascular endothelial growth factor expression (VEGF) receptor KDR/flk-1 in tumour cells in chronic myeloid leukaemia (K526 cells) were discovered." (PMID 38927266, 2024).
lymphedema (10 papers, 2018 to 2024). Excess fluid collection in tissues, causing swelling. "Additionally, genes such as KDR, BMPR2, SERPINE1, IL10, and CCL2, which have been identified as possible candidates for lymphedema through the Associative Network Discovery System, are associated with HGF." (PMID 38791500, 2024).
type 1 diabetes (10 papers, 2012 to 2024). "Type 1 diabetes did not influence the postpartum CD133+KDR+/CD133+ cell ratio compared to controls." (PMID 28278173, 2017).
invasive breast carcinoma (9 papers, 1999 to 2023). A carcinoma that infiltrates the breast parenchyma. "In invasive breast cancer, expression of Flt-1 and KDR has been observed in 44 and 38% of cases, respectively." (PMID 15841074, 2005).
liver disease (9 papers, 2013 to 2025). "Having demonstrated the uptake of siRNAs by the specific cell type of interest, we further determined their ability to specifically knockdown the endogenous (over)expression of KDR, which is a hallmark of portal hypertension that contributes to disease progression and aggravation." (PMID 29093528, 2017). "Our results demonstrate the efficacy of this improved treatment modality to specifically knockdown the disease-induced KDR overexpression, and robustly attenuate the severity of portosystemic collateral vessels in a murine model of portal hypertension." (PMID 29093528, 2017). "This means that KDR could be an excellent therapeutic target for portal hypertension and chronic liver disease." (PMID 29093528, 2017). "Moreover, the presence of these cells is associated with the expression of VEGF receptor KDR, implying that VEGF activation may also stimulate BEC-mediated liver regeneration for human liver disease intervention." (PMID 39544362, 2024).
vascular tumors (9 papers, 2013 to 2024). "Interestingly, Prx2 has been found to be an essential antioxidant enzyme that prevents the oxidative inactivation of VEGF receptor‐2 (KDR) in the vascular tumour microenvironment." (PMID 27957793, 2017).
acute coronary syndrome (8 papers, 2010 to 2025). Signs and symptoms related to acute ischemia of the myocardium secondary to coronary artery disease. "The U-shaped association of alcohol with CVD, may in part be explained by its association with sFlt-1 levels in the plasma of acute coronary syndrome patients, potentially linking the consumption of alcohol with angiogenesis via alcohol’s alternative activation of the VEGFR, KDR." (PMID 30111293, 2018). "Circulating CD34+CD133+KDR+ EPCs levels in acute coronary syndromes with affective disorders was significantly lower than that in acute coronary syndromes without affective disorder." (PMID 34421539, 2021).
dyslipidemia (8 papers, 2012 to 2025). "PIK3R2, STRA8, FLT1, DMRT1, FGF22, NR5A2, and FLT were up-regulated and PRDM14, POU5F1, and KDR were down-regulated in metabolic syndrome after exercise." (PMID 37053002, 2023). "Using univariate analysis, reduced circulating EPC level (CD34+KDR+ [cells/105 events]), metabolic syndrome, uric acid, and hsCRP were found to be significant predictors of NAFLD." (PMID 22359630, 2012).
gestational diabetes (8 papers, 2016 to 2026). Carbohydrate intolerance first diagnosed during pregnancy. "The expression of both VEGFA and KDR was reduced in gestational diabetes mellitus pregnancies compared to normal pregnancies." (PMID 38304230, 2023). "Reduction in Flt-1 expression with no change in VEGF or kinase insert domain receptor (KDR) expression was observed in gestational diabetes." (PMID 36078079, 2022).
Insulin resistance (8 papers, 2014 to 2025). Increased resistance towards insulin, that is, diminished effectiveness of insulin in reducing blood glucose levels. "We found that KDR but not KDH induced insulin resistance and damage to glucose homeostasis, while KDH induced more fat accumulation in mice, which was associated with their distinct effects on the gut microbiota and metabolite profiles." (PMID 33785628, 2021). "Combining the results that KDR but not KDH induced insulin resistance and damaged glucose homeostasis in mice, we speculated that the trans-fatty acids (TFAs) in KDR may be an important suspect." (PMID 33785628, 2021). "We found that KDR but not KDH induced glucose intolerance and insulin resistance." (PMID 33785628, 2021).
Kaposi's sarcoma (8 papers, 2003 to 2026). A malignant neoplasm characterized by a vascular proliferation which usually contains blunt endothelial cells. "The cells of dermal Kaposi’s sarcoma are associated with high levels of phosphorylated Akt, p70S6 kinase, endothelial growth factor (VEGF), and Flk–1/KDR (fetal liver kinase-1) protein." (PMID 25699089, 2014). "HHV 8 is thought to lead to Kaposi's Sarcoma through upregulation of vascular endothelial growth factor (VEGF) receptor Flk1/KDR in endothelial cells." (PMID 22654630, 2012). "Tat has been suggested to play a role in HIV-related Kaposi sarcoma by promoting EC proliferation and tumor angiogenesis, where Tat binds specifically and activates the Flk-1/kinase insert domain receptor (Flk- 1/KDR), a VEGF-A tyrosine kinase receptor, and promotes angiogenesis." (PMID 30619892, 2018). "As shown in Kaposi sarcoma cells, our studies confirm that extracellular Tat up-regulates the expression of VEGF receptor-2 (Flk-1/KDR)." (PMID 15857508, 2005).
malaria (8 papers, 2010 to 2023). Malaria is a serious and sometimes fatal disease caused by a parasite that commonly infects a certain type of mosquito which feeds on humans. "Using phosphorylated KDR antibody immunolabelling, VEGF signalling in severe malaria was demonstrated in vascular endothelial cells, glial cells and neurones." (PMID 21923924, 2011).
medulloblastoma (8 papers, 2014 to 2021). A malignant, invasive embryonal neoplasm arising from the cerebellum. "When hAT-MSCs were co-cultured with medulloblastoma-BTICs, the expression levels of CCR4, CCR5, CCR7, XCR1, CXCR1, CXCR4, PDGFR-bb, KDR and TEK were increased, while the levels of CX3CR1, IL1R, IL6R, IL8R, IGF1R and CD44 were decreased (p<0.05)." (PMID 26076490, 2015). "The KDR variant is classified as pathogenic (COSM353283) but is unlikely to be significant here, since the developing medulloblastoma benefits from a functioning KDR gene." (PMID 32419380, 2020).
pituitary tumor (8 papers, 2015 to 2025). A benign or malignant neoplasm affecting the pituitary gland. "KDR expression was 7.8-fold (p<0.0001) higher in all types of pituitary tumors combined than in normal pituitary tissue." (PMID 35600354, 2022). "Abundant expression of VEGF and KDR has been identified in pituitary glands, and VEGF participates in the formation of vascular networks in pituitary tumors." (PMID 27438154, 2016). "The pituitary contains abundant VEGF as well as KDR, and VEGF signaling participates in the neovascularization of pituitary tumors." (PMID 27438154, 2016).
interstitial lung disease (7 papers, 2018 to 2025). A diverse group of lung diseases that affect the lung parenchyma. "They describe two PAH patients with mild Interstitial Lung Disease and low DLCO who carried a loss-of-function mutation in the KDR gene." (PMID 32348326, 2020).
squamous cell lung carcinoma (7 papers, 2013 to 2024). A carcinoma arising from squamous bronchial epithelial cells. "Lung squamous cell carcinoma had much less mutations as compared with LUAD, however some genes including e.g. KDR and ROS1 were frequently mutated in LUSC." (PMID 33888829, 2021).
thyroiditis (7 papers, 2012 to 2022). Inflammation of the thyroid gland. "CRISPR/Cas9 gene editing as well as use of RTK inhibitor sunitinib of VEGFR2/KDR significantly disrupted thyroid cell cycle regulation, cell growth, and downstream signal transduction, resulting in decreased colony formation and invasion abilities." (PMID 35313079, 2022).
dementia (6 papers, 2018 to 2024). Loss of intellectual abilities interfering with an individual's social and occupational functions. "The VEGF and KDR genes were related to VEGF ligand–receptor interactions and anti-inflammatory cytokine pathways, which may contribute to CI-related dementia." (PMID 33352859, 2020).